EGFR (epidermal growth factor receptor)
Diseases named in the same sentence as EGFR in open-access papers (continued):
Sharing a sentence is not in itself a finding about the gene and the disease.
tumor (continued). "The integration of molecular imaging biomarkers into standard clinical protocols after injection could address these limitations, providing a global representation of tumor target expression and accessibility, enabling image-guided selection of patients for EGFR-targeted therapies." (PMID 30213849, 2019). "Interestingly, this phenotype could be recapitulated by tumor regression mediated by deprivation of the EGFR oncogene indicating that tumor regression alone was sufficient for these immunostimulatory effects." (PMID 31291990, 2019). "In addition, tumor cells were also reported to overcome IGF1R inhibition in an EGFR-dependent manner, indicating that EGF signaling could be another way mediating IGF1R blockade resistance." (PMID 30422809, 2019). "We recently conducted a monocentric study, termed EMULATING (EGFR MUtation status from pLAsma: circulaTING tumor DNA analysis in NSCLC patients), which investigated the ability to detect in plasma of advanced NSCLC patients EGFR mutations previously identified in matched tumor tissue biopsy." (PMID 31861832, 2019). "These alterations could stem from EGFR-mutated tumor cells but also from tumor clones lacking EGFR mutation." (PMID 31861832, 2019). "Fourth, TKIs efficacy may be associated with patient characteristics (such as gender, race, and smoking status), tumor pathology, EGFR mutation types, and developing brain metastasis or not." (PMID 31581247, 2019). "Importantly, the mechanisms of EGFR TKI resistance elucidated to date can encompass multiple mechanisms simultaneously in one patient or even tumour, creating significant obstacles for designing better treatment strategies for patients (Pao and Chmielecki, 2010; Chong and Jänne, 2013)." (PMID 31741433, 2019). "E4orf4 protein has been linked to a cell penetrating peptide called DPT-sh1 and has also been fused to the epidermal growth factor receptor (EGFR), a receptor which is overexpressed in many cancers was shown to be internalised in cancer cell lines and could also inhibit tumour growth in nude mice." (PMID 31817939, 2019). "Thus, despite MET-amplified tumor cells potentially resistant to EGFR-TKIs may already exist at baseline, the clinical significance of these cells in intrinsic resistance requires further confirmation in large cohorts." (PMID 31266248, 2019). "Besides the cumulative anti-tumor effects, the reasons for AM prolongs PFS may be associated with its effects of inhibiting the VEGFR-2 action, reversing the EGFR-TKIs drug resistance and enhancing the body’s sensitivity." (PMID 31570733, 2019). "In addition, CTCs are being gradually employed in the detection of mutations and rearrangements in common targeted genes (EGFR, ALK, KRAS, etc.)in tumor patients, and can indicate the effect of targeted drugs during the treatment of patients with EGFR mutations and incidence of drug resistance." (PMID 31344053, 2019). "The proportion of tumor cells that respond to osimertinib might be expected to correlate with the longer PFS associated with osimertinib treatment, in consistency with the initial EGFR-TKIs." (PMID 30875919, 2019). "This could also affect a larger population of tumor cells, including cells that upregulate Met expression as a resistance mechanism against anti-EGFR therapy, and could be an advantage in tumors with heterogeneously expressed markers such as EGFR and Met." (PMID 31544832, 2019). "Conversely, EGFR could improve the growth of NON-SMALL CELL LUNG tumor." (PMID 30792708, 2019). "Hence, EGFR testing in primary tumor tissue has become a gold standard in clinical practice." (PMID 31870098, 2019). "The EGFR targeted tyrosine kinase inhibitors (TKI) erlotinib, afatinib or gefitinib are available as second-line treatments, although the latter two may only be available in some regions and limited to patients with a tumor bearing an activating EGFR mutation." (PMID 30973926, 2019).
tumor (continued). "Furthermore, it is of particular interest that 293C3-SDIE was able to induce anti-tumor immunity against microsatellite stabile (Caco-2, HT-29) and RAS-mutated (HCT-116) CRC forms, where checkpoint blockade and anti-EGFR mAbs were found to lack efficiency in patients, respectively." (PMID 31181683, 2019). "Intra-tumoral clonal heterogeneity, co-existence of the two alterations in the same tumor cells, very rapid acquisition of the co-alteration right after initiating TKI-treatment, or a combination of these circumstances have been envisioned as possible causes of EGFR/ALK co-alteration in NSCLC." (PMID 31266248, 2019). "This might represent a missed therapeutic opportunity: based on hotspot sequencing, the patient was excluded from anti-EGFR treatment and instead received chemotherapy, while PRM-based tumor-phenotyping indicates the patient might have benefitted from anti-EGFR therapy." (PMID 31805664, 2019). "However, in a subcutaneous xenograft model using Mayo39 and Mayo59 GBM cell lines, crizotinib was only effective at reducing tumour burden and vascular density when used in combination with the EGFR inhibitor erlotinib." (PMID 31616641, 2019). "Thus, the present multicenter retrospective study was conducted to verify the prognostic and predictive role of tumor site in a cohort of patients with RAS wt mCC treated with first-line chemotherapy plus Bevacizumab or anti-EGFR monoclonal antibodies in the real-word setting." (PMID 31762802, 2019). "Several studies illustrate that a substantial part of the clinical responses observed following EGFR targeting treatments may not only be mediated by direct effects on the tumour, but also by regulation of immune responses, an aspect of EGF biology that remains undervalued." (PMID 30659329, 2019). "Therefore, while successful clearance of EGFRvIII+ cancer cells would not be expected to affect EGFR wt neighbors, it has the potential to render the tumor significantly more susceptible to conventional therapies as part of combination treatments." (PMID 30601871, 2019). "However, the anti Her2/neu CAR-T cells only demonstrated significant efficacy when epidermal growth factor receptor (EGFR) was highly expressed in the majority of cells within the tumor, whereas anti-CD24 CAR-T was successful despite low levels of CD-24 expression within the tumor." (PMID 31878090, 2019). "Firstly, Ame55 has far less in vitro capacity than cetuximab in terms of tumor cell proliferation inhibition, apoptosis promotion, cell cycle arrest, migration inhibition, and anchoring growth inhibition and has lower suppression of EGFR and its downstream phosphorylation pathway." (PMID 30733972, 2019). "In addition, ablating ITGα3 inhibited tumour growth via blockade of EGFR signalling in vivo." (PMID 30808960, 2019). "However, for some patients, it is not easy to determine the EGFR mutation status because of inadequate tumor specimen or expense." (PMID 30736438, 2019). "In this respect, it must be emphasized that NGS analysis cannot rule out whether the same tumour cell is carrying EGFR mutations and other variants or rather these mutations are present in different sub-clones." (PMID 30857358, 2019). "In addition to mutations existing in the predominant cell population of the tumor before treatment, overall resistance to therapy can arise during anti-EGFR therapy, as the drug can inhibit growth of sensitive clones, thereby allowing for expansion of initially rare RAS-mutant clones." (PMID 31616627, 2019). "Subsequently, to detect whether the sensitivity of tumor cells to EE02 increased after the overexpression of EGFR, the cancer cells were treated for 24 h, 48 h or 72 h with increasing concentrations of the inhibitor EE02 (0–5.0 μM), and then CCK-8 assays were performed." (PMID 31118055, 2019).
tumor (continued). "Reestablishing the expression of miRs using miRNA-mimics delivered via viral and non-viral (locked nucleic acids or liposomal nanoparticles) systems into the tumor tissue of NSCLC patients might provide an additional tool for suppressing tumor growth and improve the efficacy of EGFR-TKIS." (PMID 31266248, 2019). "NICE primarily recommends using FFPE tumour biopsy tissue for EGFR testing, but acknowledges that often these samples are very small and that testing cytological material may be useful where no tissue is available after the histological assessment has been carried out." (PMID 30470932, 2019). "In addition to the EGFR level, the total number of tumour cells and other microenvironment factors in vivo will affect the effect of gefitinib, which may cause the sensitization effect in vivo higher than that displayed in vitro." (PMID 31094020, 2019). "Therefore, one could speculate that, as technology improves steadily, the gap between the sensitivity of EGFR tests in tumor tissue versus cfDNA will be narrower in the future." (PMID 31861832, 2019). "In addition to their failure as monotherapy treatments, the combination of immunotherapy and TKIs did not result in a synergistic anti-tumour effect, neither in cell lines carrying EGFR mutations and PD-L1 upregulation nor in patients." (PMID 31554160, 2019). "The reduction in EGFR-mediated function in cultured U87 tumor cells by treatment with the clone 967 plasmid DNA encapsulated within THLs targeted with the HIRMAb was demonstrated by measurement of intracellular calcium flux in these tumor cells treated with the EGF peptide." (PMID 31998120, 2019). "We examined whether high PD-L1 expression, tumor mutational burden (TMB), and presence of targetable mutations (EGFR, BRAF, ERBB2, RET or ALK translocations, ROS1 rearrangements) occur at different frequencies in tumors from black patients compared to non-black patients." (PMID 31645901, 2019). "Conversely, we did not detect any EGFR mutations using Sanger sequencing, which could be attributed to the low sensitivity and need for high-quality tumor samples of this technology." (PMID 31141932, 2019). "Moreover, the 89Zr-DFO-ZTaq–related radioactivity in the CAL27 tumor (EGFR++++) was negligible." (PMID 30213849, 2019). "Our analysis revealed that P848L (a) does not bind erlotinib; (b) is turned over less rapidly than L858R (a common tumor‐derived EGFR mutation); (c) is not autophosphorylated at Tyr 1045 [the major docking site for Cbl proto‐oncogene (c‐Cbl) binding]; and (d) does not bind c‐Cbl." (PMID 31314158, 2019). "However, resistance to EGFR-TKIs still occurs and leads to tumor recurrence." (PMID 31619200, 2019). "Analysis of matched tumor and ctDNA during anti-EGFR targeted treatment uncovered mechanisms of secondary resistance to EGFR blockade and concluded that liquid biopsies could be a more robust alternative to tissue to track the genomic evolution of advanced CRC." (PMID 31752125, 2019). "However, PIT may be less effective when a tumor lacks “overwhelming” expression of a single target such as EGFR." (PMID 30765854, 2019). "Therefore, as an EGFR-driven tumor, the role of ErbB3 in HNSCC is somewhat unclear." (PMID 29305574, 2018). "Importantly and in agreement with patient survival data, xenografts from EGFR and c‐Fos double‐positive 143b cells were more aggressive, resulting in significantly shorter median survival and twofold to threefold increased tumor progression as compared to LM7‐derived tumors." (PMID 30361264, 2018). "Furthermore, Lycorine impaired GBM tumor growth in three different xenograft models (an U251-luc intracranially orthotopic transplantation model, an EGFR stably knockdown U251 subcutaneous xenograft model and a patient-derived xenograft mouse model), dependent on EGFR overall expression." (PMID 30016965, 2018).
tumor (continued). "Therefore, immuno-PET might provide a valuable strategy for evaluating EGFR expression level in tumor and predicting tumor response to anti-EGFR-targeted therapy." (PMID 30373221, 2018). "In 134 patients identified, main tumor resection was performed in 87 (64.9%) patients, while 89 (66.4%) and 57 (42.5%) patients received postoperative chemotherapy and epidermal growth factor receptor- tyrosine kinase inhibitor (EGFR -TKI) therapy, respectively." (PMID 29435191, 2018). "Taken together, our findings from multi-region sequencing of EGFR-mutant LUAD suggest that a dominant truncal driver, in the context of low-mutation rates and high-genomic instability, likely results in early clonal selection with subsequent high-intra-tumor heterogeneity." (PMID 29335443, 2018). "Analysis of copy number variation data from COSMIC reveals that EGFR copy number gains significantly outnumber copy number losses in several tumour tissues (central nervous system, ovary, and pancreas), consistent with an oncogenic, growth-promoting role for EGFR in cancer." (PMID 29695735, 2018). "Treatment modalities such as microRNA-loaded minicells targeting epidermal growth factor receptor (EGFR) for tumor suppression, Wilms’ tumor 1 vaccines, and tyrosine kinase inhibitors could prove to be valuable additions to the standard therapeutic approaches for MPM34,50." (PMID 30410726, 2018). "Moreover, since for a subset of mCRC patients the diagnosis of metastases is done only by radiological studies, often only a primary tumor sample is available to perform molecular determinations, even if the principal goal of anti-EGFR therapy is to treat metastases." (PMID 30477151, 2018). "First, with DEPO, our analysis of druggability in a given tumor is exclusively based on mutation/drug interactions rather than gene/drug interactions, with variants including both predefined mutations (e.g., BRAF V600E) and categories of mutations (e.g., EGFR exon 19 deletions)." (PMID 30053901, 2018). "However, nanoparticle-based approaches that aim to suppress EGFR activity, like in tumor therapy, might have the side effect of an activation of this receptor pathway." (PMID 29690640, 2018). "However, one early study suggested that GPRC5A exhibits a tumor-suppressive role in EGFR-expressing MDA-MB-231 cells and that GPRC5A knockdown promotes colony formation, cell growth, cell migration and invasion capacities in this cell line, but has no such effect in EGFR-negative MCF7 cells." (PMID 30417009, 2018). "AREG-targeted therapy could avoid negative side effects associated with broad EGFR inhibitors, but could also potentially direct tumor growth toward a less aggressive pattern." (PMID 30367629, 2018). "As well as disease stage, tumor genotype could also be an important determinant of culture success in these conditions: previous studies focus on biopsies and plural effusions from EGFR‐mutant/ALK‐positive tumors, while 7 of our 10 LUAD tumors were driven by mutant KRAS." (PMID 29569246, 2018). "We were able to show that low EGFR mRNA expression and low HIF-1α mRNA expression are associated with a poorer prognosis for STS patients, but in particular, the combination of both markers appears to be a helpful tool to assess the risk of tumor-related death of STS patients." (PMID 30513863, 2018). "However, there is no consensus on the optimal detection method to identify EGFR mutations and the sources of tumour material (biopsy tumour tissue samples, cytology specimens or serum samples) have been a notable consideration in EGFR mutation detection." (PMID 29382302, 2018). "Thus, our results indicate that the ddEGFR test is more sensitive for EGFR mutation detection, independent of tumor ratio." (PMID 29323170, 2018). "Thus, in tumors with an altered RTK signaling the interaction of PTPIP51 and c-Src may constitute a tumor-interspecies mechanism of anti EGFR therapy resistance." (PMID 30360441, 2018).
tumor (continued). "Most receptor tyrosine kinases—such as EGFR—act as oncogenes, but publicly available data from the Cancer Cell Line Encyclopedia (CCLE) indicates copy number loss in the ERBB4 RTK gene across dozens of GBM cell lines, suggesting a potential tumor suppressor role." (PMID 29342193, 2018). "Moreover, the EGFR protein level was downregulated by silencing of SCIN in all tumour tissues." (PMID 29744289, 2018). "The tumor from patient CTC15035EML4–ALK and the CTC15035EML4–ALK xenografts generated from it contained the EML4–ALK gene fusion, and the tumor from patient CTC15063EGFR L858R, T790M and the CTC15063EGFR L858R, T790M xenografts generated from it contained the EGFR mutations, L858R and T790M." (PMID 29764505, 2018). "In agreement with other published studies, we demonstrated that main tumor resection could confer a survival benefit in patients with negative or unknown EGFR mutation status." (PMID 29435191, 2018). "Our results also suggested that 64Cu-PCTA-cetuximab could be used to treat peritoneal dissemination of tumor cells expressing EGFR, with or without a KRAS mutation." (PMID 29989003, 2018). "Tracking EGFR mutations alone in plasma during EGFR‐targeted therapy may not accurately reflect tumour burden due to underlying tumour heterogeneity." (PMID 29848757, 2018). "Besides its crucial role in the tumor development, the KRAS mutational status is also critical for the antiepidermal growth factor receptor (EGFR) therapy management in colorectal cancers, which has greatly improved the clinical outcome of the disease in the past decade." (PMID 30406144, 2018). "EGFR amplification and MLH1 deletion are associated with poor prognosis, regardless of whether the tumor harbors an EGFR or MLH1 mutation." (PMID 30526857, 2018). "For instance, in NSCLC patients with acquired resistance to anti-PD-1/PD-L1 immunotherapies and EGFR or ALK mutations, particularly for patients with high tumor burden or rapid disease progression, a combination of anti-PD-1/PD-L1 therapy and targeted therapy may be an option." (PMID 30159341, 2018). "Indeed, humanized monoclonal antibodies (huAb), directed to receptors involved in the proliferation of tumor cells, including EGFR or Her2b, may hit MSCs that share these molecules at the cell surface." (PMID 29515580, 2018). "Until then, the absence of EGFR mutations in LB might not necessarily indicate that the tumor is indeed negative for these mutations and the complementary testing of a tissue biopsy is recommended." (PMID 29719623, 2018). "However, compound EGFR mutations with or without classical mutations have been detected within the same tumour tissues in some patients." (PMID 30055651, 2018). "Interestingly, of the four patients with a wild type primary tumor, two showed no mutations, while, among the others, one showed EGFR p.E746_A750del, and the other the KRAS p.G12V mutation." (PMID 30110953, 2018). "In addition, baseline pEGFR was low in HNC002, suggesting that this tumor might be less dependent on EGFR-related pathways for tumor growth." (PMID 29983881, 2018). "However, blocking EGFR signaling has provided less therapeutic benefit than initially anticipated and this may be largely related to the cellular heterogeneity of tumours and, particularly, to the presence of sub-populations of CSCs and differentiating cells." (PMID 29568372, 2018). "Additionally, the EGFR inhibitor erlotinib was shown to prolong survival in unselected NSCLC patients after first- or second-line chemotherapy, suggesting that some wild-type EGFR tumours may be sensitive to EGFR inhibition." (PMID 30119639, 2018).